IL6 (interleukin 6)
Diseases named in the same sentence as IL6 in open-access papers (continued):
Sharing a sentence is not in itself a finding about the gene and the disease.
thyroid (44 papers, 2007 to 2026). "They observed that PD-1 inhibition triggered more severe thyroiditis with significantly elevated IL-6, whereas CTLA-4 blockade was associated with increased GM-CSF/MIP-1β and diffuse thyroid enlargement." (PMID 40909293, 2025). "Interleukin-6 (IL-6), a cytokine associated with inflammation, was proposed as a biomarker to distinguish between amiodarone-induced thyroiditis and iodine-induced hyperthyroidism." (PMID 25477968, 2014). "Moreover, TSH itself can act as a cytokine in thyroid diseases and is associated with the continuous release of IL-1, IL-2, IL-6, and IL-12 by lymphocytes and dendritic cells, further enhancing immune responses and mast cell activation." (PMID 40075855, 2025). "Thus, it was hypothesised that IL-6, a proinflammatory cytokine, and one of the chief components of the underlying inflammatory conditions, may help in differential diagnosis of thyroid diseases." (PMID 27034885, 2016). "Immunological evaluation revealed B lymphocyte expansion, elevated interleukin-6 and interleukin-8 levels, and strong thyroid autoantibody positivity consistent with Graves' disease, while anti-ganglioside and paraneoplastic antibodies were negative." (PMID 42233015, 2026). "Pathogenetic mechanisms potentially include direct thyroid damage via ACE2 receptors and indirect injury through immune dysregulation, particularly IL-6-mediated thyroiditis." (PMID 40162434, 2025). "The levels of IL6 and IL8 are also positively associated with thyroid hormone levels in patients with thyroid disorders." (PMID 39525855, 2024). "On the other hand, overexpression of CD40 is able to activate downstream cytokines, such as IL6, which increase the production of thyroid-specific autoantibodies and promote hyperthyroidism." (PMID 38586452, 2024). "We then used Spearman correlation analysis to evaluate relationships of IL-6 and IL-8 with thyroid parameters and clinical characteristics." (PMID 39525855, 2024). "Further cytokine profiling demonstrated that anti-PD-1 induced a 5-fold increase in blood IL-4, compared to baseline, and IL-6 levels were correlated with severe thyroid histopathology." (PMID 39247203, 2024). "IL-6 plays an essential role in thyroid disease progression, and by IL-6 signaling, thyroid disease can be managed." (PMID 37241088, 2023). "In TC, IL-6 is dependent on the activation of the IL6/JAK1/STAT3 signaling pathway to promote thyroid CSC proliferation and colony formation and to enhance the properties of thyroid CSCs and EMT." (PMID 35479325, 2022). "Specifically, a hyper-activation of the Th1/Th17 response has been reported in patients with autoimmune and drug-induced thyroiditis, and an increase in IL-6 was described in the progress of destructive thyroiditis." (PMID 35625425, 2022). "Inflammatory cytokines (e.g., interleukin-6, tumour necrosis factor, and interferon-α) which are related to thyroid function abnormalities are also involved in the pathogenesis of ICUAW." (PMID 34621547, 2021). "Serum level of IL-6, IL-7, IL-10, and IL-13 was higher in thyroid disease, while IL-8 was lower than healthy controls." (PMID 32655554, 2020). "Serum IL-6 and IL-8 were higher in presurgical thyroid samples and returned to normal following surgery." (PMID 32655554, 2020). "This study also found a “significant correlation” between IL-6 and free T4, total T4, and total T3, which could imply a role for proinflammatory cytokines in the development of painless thyroiditis." (PMID 39967901, 2024). "Besides, during the COVID-19 pandemic, the SARS-CoV-2 coronavirus can trigger an overactive immune response and an increase in interleukin-6 levels, potentially leading to thyroiditis." (PMID 38715797, 2024). "This suggests that IL17, IL6 and GMCSF cytokines may be pathogenic in ICI-thyroiditis." (PMID 39247203, 2024). "The results showed that enhanced IL-6 levels could predict the occurrence of thyroiditis." (PMID 36159840, 2022).
thyroid (continued). "A positive relationship between hs-CRP, IL-6 and NT-pro-BNP was established in our study indicating that thyroid function disturbances contribute to inflammatory processes even during the rehabilitation period (i.e., after acute coronary events)." (PMID 26892923, 2016). "Therefore, IL-6, IL-15, and TNF-α were selected as representative indicators in this study to explore the potential interplay among thyroid function, inflammatory state, and skeletal muscle metabolism." (PMID 41355999, 2025). "Inflammatory markers such as IL-6 may be elevated in AIT 2, indicating ongoing thyroiditis; however, some patients with AIT 2 have been found to have low IL-6 levels, likely due to the assay being used, limiting its overall usefulness." (PMID 39100009, 2024). "In this small series of patients, a comparison of symptoms allowed the following findings: symptoms consistent with painless thyroiditis presented earlier after COVID-19 infection than their comparator, and their levels of serum CRP and IL-6 were significantly higher." (PMID 39967901, 2024). "Marked elevations of IL-6 levels correlated closely with subacute thyroiditis in patients without preexisting thyroid disease." (PMID 25477968, 2014). "Elevated IL-6 was not demonstrated in any other thyroid disease manifested by thyrotoxicosis." (PMID 30936776, 2019). "Previous results from our group demonstrated that ouabain (10−7 M) increased IL-6 and IL-6R mRNA levels in TPC-1, BCPAP (papillary carcinoma human thyroid cell lines) and NTHY-ori (non-tumoral human thyroid cell line) after 24 h of culture." (PMID 36551653, 2022). "Different models of thyroid damage applied in the experiment resulted in no significantly different effects on the TNF-α, IL-6, and IL-10 levels." (PMID 30927245, 2020).
hemorrhage (43 papers, 2010 to 2026). Loss of blood from the vascular compartment to the exterior or into nonvascular body space as a result of rupture or severance of the blood vessels. "In Brazilian individuals, high levels of IL-6, L-8, and IFN-γ were associated with death from kala-azar, higher levels of L-8 and IFN-γ were evident in cases with hemorrhage, and IL-6 and IFN-γ were associated with increased coagulation markers." (PMID 41003560, 2025). "For example, polymorphisms in IL6 have been associated with hemorrhage in patients with sporadic BAVM." (PMID 34479577, 2021). "This led to the identification of statistically significant association between bAVM-related hemorrhage and twelve heritable variants of seven genes (IL6, APOE, IL1B, IL17A, MMP9, EPHB4, and VEGFA) involved in the inflammatory and angiogenic signaling pathways." (PMID 37065486, 2023). "Patients with early hematoma growth exhibit higher baseline serum IL-6 levels, which has also been correlated with the size of perihematomal hypodensity 3–4 days post-hemorrhage." (PMID 39970158, 2025). "Studies by Audrey C. Leasure and colleagues found that higher IL‐6 concentrations in ICH patients were associated with poorer functional outcomes and larger hemorrhage volumes." (PMID 39853806, 2025). "Twelve single nucleotide polymorphisms (SNPs), including IL6 rs1800795, IL17A rs2275913, MMP9 rs9509, VEGFA rs1547651, and EPHB4 rs314353, rs314308, and rs314313, were associated with bAVM-related hemorrhage." (PMID 37065486, 2023). "This in stark contrast to the average maximum fold change for IL-1ra and IL-6 in our previously reported polytrauma and hemorrhage model, which was 2286 and 785, respectively." (PMID 36930612, 2023). "Our study found that the intervention of ENA reduces the expression of TNF‐α, IL‐1β, and IL‐6 in the tissues around the hematoma lesion after hemorrhage, thereby reducing the inflammatory injury." (PMID 37614117, 2023). "We summarized that SNPs of five inflammatory genes (IL6, APOE, IL1B, IL17A, MMP9) were reported to be associated with bAVM-related hemorrhage." (PMID 37065486, 2023). "Trauma-hemorrhage is known to increase the expression of pro-inflammatory mediators, such as the early mediator interleukin 6 (IL-6), which increases the expression of other cytokines, chemokines and adhesion molecules." (PMID 28817064, 2017). "Specifically, effects of RES on ER include anti-inflammatory effects such as protection from trauma-hemorrhage-induced injury and suppression of Interleukin-6 (IL-6) expression in the liver, intestine and cardiovascular system." (PMID 28915830, 2017). "Specifically, effects of resveratrol on ER include anti-inflammatory effects such as protection from trauma-hemorrhage-induced injury and suppression of Interleukin-6 (IL-6) expression in the liver, intestine, and cardiovascular system." (PMID 24771768, 2014). "Others have suggested that elevated plasma TNF-α and IL-6 induced by trauma-hemorrhage was prevented by estradiol treatment in rats." (PMID 24945834, 2014). "From this study, maraviroc activated hepatic PPARγ and decreased hepatic ICAM-1 and IL-6 levels and neutrophil activity following trauma-hemorrhage." (PMID 24205332, 2013). "The effects of these treatments were then examined with respect to hepatic injury as well as hepatic myeloperoxidase (MPO) activity, intercellular adhesion molecule-1 (ICAM-1), interleukin-6 (IL-6), and PPARγ levels following trauma-hemorrhage." (PMID 24205332, 2013). "The present study investigates the effects of femoral shaft fracture, isolated or in combination with hemorrhage, on early stage cytokine production capacity of splenocytes and observes the role of IL-6 under these conditions." (PMID 22496597, 2012). "In conclusion, this study indicates that astringinin administration ameliorates hepatic injury and IL-6 production after trauma-hemorrhage." (PMID 22022464, 2011). "CRP and IL-6 levels were markedly elevated in patients with hemorrhage or fatal outcomes." (PMID 41901712, 2026).
hemorrhage (continued). "Of note, the reports on the cytokine IL-6 and hemorrhage in patients have been conflicting." (PMID 36293431, 2022). "Our previous research found that the plasma level of IL-6 may be a predictor of hemorrhage of cerebral arteriovenous malformation." (PMID 30045256, 2018). "In addition, IL-6 is required for the expression of adhesion molecules and chemokines following trauma-hemorrhage." (PMID 24205332, 2013). "Based on our results, it could be assumed that IL-6 might exert anti-inflammatory effects on the splenic immune function after trauma-hemorrhage." (PMID 22496597, 2012). "PUGNAc and GlcN treatments also result in improved cardiac function and organ perfusion and reduced circulating levels of IL-6 and TNF-α in association with increased O-GlcNAc protein modification in the heart, liver, and kidney of rats subjected to trauma-hemorrhage." (PMID 21904602, 2011). "Patients with haemorrhage-hepatitis syndrome had lower concentrations of IFN-α, IFN-λ2/3, IL-1β and IFN-γ and higher levels of IP-10, IFN-λ1, IL-6, IL-10, TNF-α and GM-CSF." (PMID 37090924, 2023). "In the ipsilateral region (around the hemorrhage), TNF-α was significantly increased on day 3, IL-1β on days 1 and 3, and IL-6 on day 1 after ICH compared to the sham group." (PMID 37190062, 2023). "The increase in serum levels of proinflammatory cytokines IL-1α, IL-1β, IL-6, and TNF-α in the groups submitted to hemorrhage agrees with findings in other studies showing greater production of these inflammatory mediators in renal injury." (PMID 29535870, 2018). "There is evidence that the expression of certain inflammatory molecules peaks within 24 hours after hemorrhage onset, with IL-6 being elevated at days 0 to 1 after SAH though others have shown a peak of IL-6 at day 6 after SAH." (PMID 25105123, 2014). "Previous studies have shown that levels of IL-6 and TNF-α significantly increased following trauma-hemorrhage and remain elevated for several hours." (PMID 21649921, 2011).
knee osteoarthritis (43 papers, 2009 to 2025). "The study found asignificant association between serum vitamin - D levels and IL-6 concentrations in patients with knee osteoarthritis." (PMID 41170094, 2025). "PGE2 for instance is the best known lipid mediator that contributes to inflammatory pain in arthritic conditions, while IL-6 is also associated with hyperalgesia and hypersensitivity in joint tissues 26 and play a critical role in pain at least in the early stage of knee osteoarthritis OA27." (PMID 33177650, 2020). "TMJ osteoarthritis and knee osteoarthritis are considered as low-inflammatory arthritic conditions, with increased pro-inflammatory cytokines in the synovial fluid such as IL-1beta, IL-6, TNF-alpha, and PGE2." (PMID 38391657, 2024). "PRP treatment for knee osteoarthritis effectively lowers the concentrations of inflammatory factors IL-6, IL-1β, TNF α, IL-17A, and IL-10, significantly alleviating knee joint pain and enhancing joint functionality." (PMID 37869166, 2023). "This is consistent with the results of 10.6 μm laser moxibustion on IL6, TNFα and IL1β in knee osteoarthritis animal models." (PMID 37593350, 2023). "Here, we showed that CSF obtained from a cohort of patients with chronic knee pain secondary to knee osteoarthritis when added together with LPS, was able to stimulate T98G cells to release IL-6." (PMID 32213162, 2020). "In this study, we investigated the ability of CSF from patients diagnosed with knee osteoarthritis suffering from chronic pain, to trigger the release of pro-inflammatory cytokines, IL-6, IL-1beta and tumour necrosis factor alpha (TNF-α) from T98G." (PMID 32213162, 2020). "In patients with knee osteoarthritis, the consumption of A. lappa root tea for 42 days decreased the levels of serum IL-6, CRP, and MDA." (PMID 31771282, 2019). "Recently, we observed IL‐6‐secretion by CD4+ T cells from the stromal vascular fraction (SVF) of the infrapatellar fat pad (IFP) of knee osteoarthritis patients directly ex vivo." (PMID 29283192, 2018). "In this study, we investigated IL‐6+CD4+ T cells present in the SVF of the IFP in knee osteoarthritis patients." (PMID 29283192, 2018). "In summary, patients with early- and late-stage post-traumatic knee osteoarthritis have increased levels of circulating proinflammatory nitrite/nitrate (NOx), IL-6, and uric acid compared with healthy subjects." (PMID 29058227, 2017). "In the context of knee osteoarthritis, inflammatory cytokines such as IL-6 and TNF-α may affect bone marrow function and iron metabolism, thereby influencing RDW levels." (PMID 40755482, 2025). "Furthermore, the IGF‐1 and IL‐6 changes elicited in our study synergistically align with reducing proinflammatory markers and mitigating cartilage and synovium damage in knee osteoarthritis and cartilage repair animal models." (PMID 41180562, 2025). "A randomized controlled trial demonstrated that a 4-week course of TFM treatment could alleviate knee osteoarthritis symptoms by reducing IL-6 and tumor necrosis factor levels." (PMID 40134594, 2025). "Additionally, higher ratios of IL-10/TNF-γ, IL-10/IL-12, and IL-10/IL-6 confirmed the predominance of anti-inflammatory over proinflammatory mediators in the serum of gonarthrosis patients with DM." (PMID 36141752, 2022). "In our study, IL6 was significantly increased in knee osteoarthritis synovial membranes." (PMID 31139654, 2019). "For example, higher IL6 were reported in both the synovial fluid and serum of patients with hip osteoarthritis, whereas serum leptin levels have been reported to be higher in patients with knee osteoarthritis." (PMID 29225423, 2017). "In patients with knee osteoarthritis assessed before and after bariatric surgery, the surgery led to a significant decrease in BMI (20%) with improvement in pain standards and knee function, and a reduction in levels of markers of articular destruction, serum IL-6, CPR, and leptin." (PMID 28226002, 2017).
knee osteoarthritis (continued). "Unbalanced remodeling of the articular cartilage driven by inflammatory mediators, including IL-1beta, IL-6, and TNF-α, is a significant contributing factor to the development and progression of knee osteoarthritis." (PMID 40636390, 2025). "Intra-articular autologous injection of BMSCs into the knee joint of patients with knee osteoarthritis reduces serum TNF-α and IL-6 levels and significantly improves pain and clinical scores compared with endoscopic synovectomy and hyaluronic acid injection." (PMID 36766847, 2023). "Results from our study clearly showed that gonarthrosis patients with DM had significantly lower systemic values of proinflammatory cytokines TNF-α, IL-6, IL-12, IFN-γ, and IL-17." (PMID 36141752, 2022). "Lower proinflammatory cytokines in gonarthrosis patients with DM were accompanied by higher ratios of IL-10/TNF-γ, IL-10/IL-12, and IL-10/IL-6, underpinning the predominance of anti-inflammatory over proinflammatory mediators." (PMID 36141752, 2022). "We showed previously that adjunct resveratrol supplementation with NSAID reduces pain and inflammation reflected as a significant reduction of serum levels of the proinflammatory markers including IL-6, IL-1β, and TNF-α in patients with knee osteoarthritis." (PMID 34805399, 2021). "Then, our data showed that umbilical cord MSCs reduced NO, IL-6, and TNF-α in serum and joint fluid and attenuated the inflammatory response in an animal model of knee osteoarthritis." (PMID 35095776, 2021). "The statistical result of the verification experiment showed that the expression level of ADIPOQ, IL6, and CXCR1 was significantly increased in knee osteoarthritis synovial membranes (p < 0.05)." (PMID 31139654, 2019). "Therefore, it is of interest to evaluate the associationbetween serum vitamin D levels, pro-inflammatory cytokines (IL-6, TNF-α), and functional status in patients with knee osteoarthritis(OA)." (PMID 41170094, 2025). "However, in a study of patients with knee osteoarthritis, a reduction in pro-inflammatory molecules (MMP-2, IL-1B, IL-6, and IL-8) and an increase in anti-inflammatory molecules (IGF-1 and IL-10) were found at the 1-year follow-up after an SVF injection." (PMID 38391657, 2024). "From this experiment, our findings suggest that the YTPS ethanolic extract exerts anti-inflammatory properties through the reduction in IL-6 and TNF-α secretion, the two main pro-inflammatory cytokines found at high levels while the inflammation of knee osteoarthritis occurs." (PMID 39204123, 2024). "In our study, lower values of TNF-α, IL-6, and IFN-γ in patients with gonarthrosis and DM may explain the lower values of the WOMAC index." (PMID 36141752, 2022). "Significantly higher Gal-3/TNF-α (p = 0.001), Gal-3/IL-6 (p = 0.004), and Gal-3/IL-12 (p = 0.001) and lower Gal-3/IL-17 (p = 0.001) were detected in gonarthrosis patients with DM compared to gonarthrosis patients without DM." (PMID 36141752, 2022). "IL-10/TNF-α (p = 0.001), IL-10/IL-6 (p = 0.001), and IL-10/IL-12 (p = 0.001) were significantly higher, while IL-10/IL-17 (p = 0.001) ratio was significantly lower in gonarthrosis patients with DM compared to gonarthrosis patients without DM." (PMID 36141752, 2022). "Systemic values of proinflammatory TNF-α, IL-6, IL-12, IFN-γ, IL-17, and Gal-3 in gonarthrosis patients with DM were significantly lower than in gonarthrosis patients without DM." (PMID 36141752, 2022). "Significantly lower concentration of TNF-α (p = 0.001), IL-6 (p = 0.001), IL-12 (p = 0.001), IL-17 (p = 0.001), IFN-γ (p = 0.014), and Gal-3 (p = 0.040) was found in gonarthrosis patients with DM compared to gonarthrosis patients without DM." (PMID 36141752, 2022). "We observed lower serum levels of Gal-3 as well as TNF-α, IL-6, IL-12, IFN-γ, and IL-17 in gonarthrosis patients with DM compared to gonarthrosis patients without DM." (PMID 36141752, 2022).